SGO1 (shugoshin 1)
Diseases named in the same sentence as SGO1 in open-access papers (continued):
Sharing a sentence is not in itself a finding about the gene and the disease.
neuroblastoma (2 papers, 2016 to 2024). Neuroblastoma (NB) is the most common solid, extracranial childhood tumor. "With the exception of Stag2, expression of all cohesin subunits increased during neuroblastoma progression, as in the case of Sgo1." (PMID 27539729, 2016). "SGO1 knockdown induced DNA damage in MYCN-overexpressing neuroblastoma cells, resulting in G2/M accumulation." (PMID 27539729, 2016). "Together, these observations indicate that SGO1 is required for efficient progression through G2/M phase in MYCN-overexpressing neuroblastoma cells." (PMID 27539729, 2016). "In MYCN-overexpressing neuroblastoma cells, SGO1 knockdown induced DNA damage even in interphase, and this phenotype was independent of cohesin." (PMID 27539729, 2016). "We also examined the impact of SGO1 knockdown on several neuroblastoma cell lines and found that SGO1 knockdown severely inhibited the proliferation of MYC-amplified cell line (IMR32)." (PMID 27539729, 2016). "Next, to determine whether SGO1 affects proliferation of neuroblastoma cells, we knocked down SGO1 in MYCN-overexpressing SH-EP cells using short hairpin RNA (shRNA)." (PMID 27539729, 2016). "Therefore, we propose that SGO1 represents a potential molecular target for treatment of MYCN-amplified neuroblastoma." (PMID 27539729, 2016). "Therefore, we propose that SGO1 is a potential molecular target for the treatment of MYCN-amplified neuroblastoma and tumors bearing YAP/TAZ hyperactivation." (PMID 27539729, 2016). "However, the role of SGO1 during interphase in cancer cells in general, and in neuroblastoma in particular, remains unclear." (PMID 27539729, 2016). "Downregulation of SGO1 impaired proliferation and induced DNA damage followed by a senescence-like phenotype only in MYCN-overexpressing neuroblastoma cells." (PMID 27539729, 2016). "Together, these results showed that SGO1 is elevated in MYCN- or MYC-overexpressing cancers, including neuroblastoma cell lines showing MYCN amplification." (PMID 27539729, 2016). "Likewise, SGO1 mRNA and protein levels were higher in MYCN-amplified neuroblastoma cell lines (IMR32, SK-N-BE, and NB39) than in a neuroblastoma cell line harboring a single copy of MYCN (SK-N-AS)." (PMID 27539729, 2016). "In contrast to SGO1 knockdown, however, cohesin subunit knockdown did not significantly alter the cell-cycle profile, even in MYCN-overexpressing neuroblastoma cells." (PMID 27539729, 2016).
esophageal carcinoma (1 paper, 2025). A primary or metastatic malignant neoplasm involving the esophagus. "The top four tumors most significantly correlated with expression of SGO1 were GBM, STAD, TGCT, and SKCM (Stromal score), GBM, STAD, KIRC and THCA (Immune score), GBM, STES (stomach and esophageal carcinoma), STAD, and SKCM (ESTIMATE score) respectively." (PMID 40861810, 2025).
Hyperinsulinemia (1 paper, 2024). An increased concentration of insulin in the blood. "Additionally, hyperinsulinemia inhibited the transcriptome required for cell cohesion MELK, CDCA7, ESCO2, mitotic spindle assembly KIF15, SGO1, and AURKB, and kinetochore formation KNL and NDC80." (PMID 39768214, 2024).
intestinal pseudo-obstruction (1 paper, 2025). A type of ILEUS, a functional not mechanical obstruction of the INTESTINES. "Four additional patients were diagnosed based on the combination of digestive symptoms of intestinal pseudo‐obstruction and the presence of the SGO1 (p.Lys23Glu) mutation." (PMID 41245052, 2025).
leukemia (1 paper, 2015). A malignant (clonal) hematologic disorder, involving hematopoietic stem cells and characterized by the presence of primitive or atypical myeloid or lymphoid cells in the bone marrow and the blood. "The expression level of Sgo1 was also elevated in leukemia cell lines derived from hematological malignancies." (PMID 25638162, 2015).
liver cancer (1 paper, 2016). An epithelial or non-epithelial malignant neoplasm that arises from the liver. "Previously Shugoshin-1 (Sgo1−/+) mice, a transgenic mouse model of CIN, showed mild proneness to spontaneous lung and liver cancers." (PMID 27526110, 2016).
liver cirrhosis (1 paper, 2015). "Besides these two parameters, the level of Sgo1 in HCC did not correlate with sex, liver cirrhosis, hepatitis B virus (HBV) positivity, vascular invasion, tumor size, differentiation and staging." (PMID 25638162, 2015).
lymph node metastasis (1 paper, 2022). "An increased SGO1 expression was correlated with preoperative prostate-specific antigen, lymph-node metastasis, advanced clinicopathological characteristics, and poor recurrence-free survival time." (PMID 35592680, 2022).
mesothelioma (1 paper, 2025). A usually malignant and aggressive neoplasm of the mesothelium which is often associated with exposure to asbestos. "We observed that high expression levels of SGO1 are significantly related poorer overall survival (OS) in most cancers, including ACC, KIRP, KIRC, LIHC, LGG (brain lower grade glioma), LUAD, MESO (mesothelioma), PAAD, SKCM, and SARC (sarcoma)." (PMID 40861810, 2025).
non-small cell lung carcinoma (1 paper, 2015). A group of at least three distinct histological types of lung cancer, including non-small cell squamous cell carcinoma, adenocarcinoma, and large cell carcinoma. "Recently, overexpression of Sgo1 variant B was found in non-small cell lung cancer." (PMID 25638162, 2015).
ovarian carcinoma (1 paper, 2025). A malignant neoplasm originating from the surface ovarian epithelium. "The results showed that SGO1 expression was significantly elevated in most cancer tissues, including breast, lung, stomach, liver, colorectal, and ovarian cancers, compared with normal tissues." (PMID 40861810, 2025).
ovarian serous cystadenocarcinoma (1 paper, 2025). A malignant serous cystic epithelial neoplasm arising from the ovary. "There is a substantial positive connection between SGO1 CNV and mRNA expression in BLCA, CESC, COAD, SARC, HNSC, SKCM, OV (ovarian serous cystadenocarcinoma), PARD, BRCA, LIHC, KIRC, ESCA, UCS (uterine carcinosarcoma), UCEC, READ, PAAD, and STAD." (PMID 40861810, 2025).
pancreatic cancers (1 paper, 2015). "Overexpression of Sgo1 has been reported in breast and pancreatic cancers." (PMID 25638162, 2015). "Besides HCC, as shown in this study, upregulation of Sgo1 was found in expression datasets of breast and pancreatic cancers." (PMID 25638162, 2015).
cancer (21 papers, 2014 to 2025). A tumor composed of atypical neoplastic, often pleomorphic cells that invade other tissues. "It was concluded that SGO1 was a reliable pan-cancer biomarker, and it had good diagnostic and prognostic value in a variety of cancers." (PMID 40861810, 2025). "Alterations in the expression and function of SGO1 have been linked to tumorigenesis, enhanced cell proliferation, and poor patient prognosis across multiple cancer types." (PMID 40861810, 2025). "Existing evidence has established a positive correlation between BUB1 with PD-L1 40, and our pan-cancer analysis confirms SGO1 is linked to PD-L1 across most cancers." (PMID 40861810, 2025). "Our findings indicate that altered levels of SGO1 expression are significantly associated with cancer development and progression, highlighting its potential role as a pivotal player in tumor biology." (PMID 40861810, 2025). "These comprehensive analyses demonstrate that SGO1 expression is strongly associated with tumor stemness across diverse cancer types, suggesting its potential role as a pan-cancer stemness regulator." (PMID 40861810, 2025). "Previous studies have reported SGO1's regulatory roles in isolated cancer types, but its pan-cancer significance and underlying mechanisms remain undefined." (PMID 40861810, 2025). "GSEA enrichment confirmed that SGO1 was significantly associated with cell cycle, focal adhesion, pathway in cancer, apoptosis, oxidative phosphorylation, Wnt signaling pathway, cytokine–cytokine receptor interaction, and chemokine signaling pathway." (PMID 35592680, 2022). "In addition, high expression of SGO1 is not only associated with poor prognosis in patients but also closely related to the pathological stages of cancers." (PMID 40861810, 2025). "In some cancer cell-lines, SGO1-depletion causes G2/M arrest, apoptosis, and mitotic cell death." (PMID 33953173, 2021). "Furthermore, our exploration of gene mutations connected to SGO1 highlights the potential mechanisms through which SGO1 may influence cancer pathophysiology." (PMID 40861810, 2025). "SGO1 overexpression in tumors and its altered interaction networks generate cancer-specific vulnerabilities with therapeutic potential." (PMID 40861810, 2025). "This study bridges bioinformatics with functional validation, offering new mechanistic insights and therapeutic avenues for SGO1-driven cancers." (PMID 40861810, 2025). "Compared to normal tissues, the expression levels of SGO1 were significantly higher in 17 cancer types." (PMID 40861810, 2025). "To examine the spearman association between SGO1 CNV and gene expression and survival, we performed an analysis of pan-cancer using the GSCA platform." (PMID 40861810, 2025). "Recent studies have begun to uncover the broader implications of SGO1 beyond its traditional functions, suggesting its involvement in various cancer types." (PMID 40861810, 2025). "This study systematically investigates SGO1 in 33 cancer types, integrating multi-omics analyses and functional validation to reveal its role as a pan-cancer biomarker and therapeutic target." (PMID 40861810, 2025). "In this study, we conducted a systematic bioinformatics analysis using multiple databases to determine the biological function and prognostic significance of SGO1 in pan-cancer." (PMID 40861810, 2025). "Using TCGA, GEPIA2, and HPA databases, we found SGO1 was significantly overexpressed in 19 cancer types compared to normal tissues." (PMID 40861810, 2025). "The correlation between the expression of SGO1 and the pathological stage of cancer was examined using GEPIA2's “stage Map” module." (PMID 40861810, 2025). "By advancing our knowledge of SGO1, we can potentially unlock new strategies for cancer diagnosis and treatment, ultimately improving outcomes for patients with malignancies exhibiting altered SGO1 expression." (PMID 40861810, 2025).
cancer (continued). "Our findings establish SGO1 as a novel pan-cancer biomarker, linking its expression to tumor progression, immune evasion, and genomic instability." (PMID 40861810, 2025). "The mRNA expression of SGO1 in human pan-cancer was analyzed based on the TCGA database by TIMER2.0 in log2 transformed TPM form." (PMID 40861810, 2025). "Based on STRING analysis, MEIKIN is implicated in chromosome segregation and cell cycle regulation, through interactions with key proteins such as SGO1, SGO2, PLK1, and ESPL1, all of which are known to play critical roles in cancer-associated pathways." (PMID 41463182, 2025). "As such, further exploration in both in vitro and in vivo settings is essential to fully understand the functional consequences of SGO1 regulation and to potentially translate these insights into effective cancer therapies." (PMID 40861810, 2025). "Despite these findings, the comprehensive role of SGO1 in pan-cancer remains inadequately characterized." (PMID 40861810, 2025). "We also examined the association between higher SGO1 expression and recurrence free survival (RFS) of pan-cancer." (PMID 40861810, 2025). "We also estimated SGO1 expression in paired cancer tissues and adjacent normal tissues in pan-cancer based on TCGA datasets." (PMID 35592680, 2022). "Results confirmed that SGO1 expression was significantly higher in 14 of the 18 cancers compared with normal tissue." (PMID 35592680, 2022). "To determine the mRNA expression pattern of SGO1 in various human cancers, we used TCGA and GTEx datasets to conduct analyses." (PMID 35592680, 2022). "Finding the precise mechanisms of Sgo1-mediated apoptosis will give insights into how we can induce apoptosis in cancer models with SAC activation and how to develop small molecules targeting this pathway." (PMID 29100415, 2017). "Based on these findings, we investigated the relationship between MYCN or MYC and SGO1/SGO2 expression levels using The Cancer Genome Atlas (TCGA) pan-cancer gene expression datasets." (PMID 27539729, 2016). "Such insights are critical, as enhancing anti-tumor immunity could be a viable strategy for improving patient outcomes in cancers characterized by altered SGO1 expression." (PMID 40861810, 2025). "Next, we investigated the prognostic value of SGO1 in pan-cancer." (PMID 40861810, 2025). "The analysis and experimental results of this study provided an insight that could pave the way for novel therapeutic strategies targeting SGO1 in cancer treatment." (PMID 40861810, 2025). "In addition, we used the Kaplan-Meier Plotter database to examine the prognostic significance of SGO1 in pan-cancer." (PMID 40861810, 2025). "This understanding implies that the depletion of SGO1 might be anticipated to impede cell proliferation in both normal and cancer cells, which could be considered a potential limitation of our study." (PMID 40861810, 2025). "In addition, the assessment of genomic heterogeneity related to SGO1 provides valuable context for understanding the complexity of cancer." (PMID 40861810, 2025). "Cohesion is rescued by SGO1 overexpression but not by SGO1-binding-deficient SET mutants, revealing the SET-SGO1 axis as a non-canonical CIN pathway in cancer." (PMID 40861810, 2025). "Finally, our experimental findings support the relevance of bioinformatics analyses in elucidating the role of SGO1 in cancer progression." (PMID 40861810, 2025). "In addition, we also utilized the GEPIA2 database to analyze the expression of SGO1 across multiple cancer types, incorporating normal samples from the GTEx database to expand the sample size of normal tissues." (PMID 40861810, 2025). "Therefore, the results indicated that SGO1 expression was tightly correlated with the extent of immune infiltration in cancers." (PMID 40861810, 2025). "However, our findings have revealed the significance of SGO1 in tumorigenesis and cancer development." (PMID 40861810, 2025).
cancer (continued). "Therefore, we recognize that the relationship between SGO1's physiological function in centromeric cohesion protection and its role as a potential cancer target is complex and requires a dialectical perspective." (PMID 40861810, 2025). "On the other hand, the role of SGO1 in cancer is complex and context-dependent." (PMID 37122033, 2023). "Results suggested that SGO1 was upregulated in 26 of the 33 cancers compared with normal tissue." (PMID 35592680, 2022). "Furthermore, MYCN-promoted SGO1 transcription and SGO1 expression tended to be higher in MYCN- or MYC-overexpressing cancers." (PMID 27539729, 2016). "Therefore, the expression level of SGO1 DNA methylation may be closely related to the pathogenesis of cancer." (PMID 40861810, 2025). "Therefore, in this study, we provided a comprehensive bioinformatics analysis of SGO1 in the context of pan-cancer based on multiple databases, examining its expression profiles, prognostic value, genetic mutations, and interaction with the tumor immune microenvironment." (PMID 40861810, 2025). "Furthermore, SGO1 may contribute to the development of chemoresistance, complicating treatment regimens and posing significant challenges in cancer therapy." (PMID 40861810, 2025). "Thus, the inhibition of SGO1 activity may represent a potential therapeutic intervention against cancers that progress to metastasis." (PMID 37122033, 2023). "The pan-cancer patterns, immune correlations, and BUB1 interaction uncovered here provide a roadmap for targeting SGO1 in precision oncology, either as a standalone biomarker or in combination with immune/DNA-damaging therapies." (PMID 40861810, 2025). "For the first time, we reveal positive correlations between SGO1 expression and immune checkpoint genes (PD-1, PD-L1, CTLA4) in most cancers." (PMID 40861810, 2025). "High SGO1 expression correlated with poorer overall survival (OS) and disease-free survival (DFS) in more than 10 cancers, validated by Kaplan-Meier analysis." (PMID 40861810, 2025). "In addition, we found that SGO1 is a transcriptional target of MYCN, and that SGO1 expression correlates with MYCN or MYC expression in various cancers." (PMID 27539729, 2016). "From the subset of genes that were upregulated in HCC1954 cells compared to MCF10A cells, we chose shugoshin 1 (SGOL1) and TTK, based on their relevance and novelty, since the centrosome roles of these genes are not fully understood, especially in cancer models." (PMID 25278993, 2014).